DKK3 (dickkopf Wnt signaling pathway inhibitor 3)
Diseases named in the same sentence as DKK3 in open-access papers (continued):
Sharing a sentence is not in itself a finding about the gene and the disease.
pancreatic cancer (continued). "The stable expression of DKK3 sensitizes pancreatic cancer Bxpc‐3 cell to gemcitabine, delays tumour growth and augments gemcitabine therapeutic effect in pancreatic cancer xenotransplantation model." (PMID 26395974, 2015). "To determine the expression of DKK3, we detected the DKK3 level in six human pancreatic cancer cell lines (Aspc‐1, Bxpc‐3, CFPAC‐1, MiaPaCa‐2, PANC‐1 and SW1900)." (PMID 26395974, 2015). "Next, we suggested weather DKK3 regulated EMT in pancreatic cancer by suppressed β‐catenin signalling in hypoxic conditions." (PMID 26395974, 2015). "Further, ectopic expression of DKK3 inhibits nuclear translocation of β‐catenin induced by hypoxia in pancreatic cancer Bxpc‐3 cell." (PMID 26395974, 2015). "This is consistent with recent studies in pancreatic tumors that demonstrated increased T cell accumulation in DKK3-KO mice and others showing greater tumor rejection with enhanced CD8+ T cell infiltration into tumors when mesenchymal stem cells were DKK3 deficient." (PMID 37847565, 2023). "Furthermore, our study found that co-culture with DKK3-overexpressing pancreatic cancer cells upregulated IFN-γ, IL-2, and IL-17, inhibited tIL-4 and IL-10 in activated CD4+ T cells." (PMID 34391478, 2021). "Furthermore, the glucose levels in inactive CD4+ T cells co-cultured with DKK3-overexpressing pancreatic cancer BxPC-3 cells were higher than normal control group." (PMID 34391478, 2021). "Besides, our study also revealed that co-culturing with DKK3-overexpressing pancreatic cancer cells promotes the expression of CD69, CD3, CD25, CD71, and HLA-DR mRNA in CD4+ T cells." (PMID 34391478, 2021). "In this study, we hypothesized that DKK3 may affect the proliferation and function of CD4+ T cells by regulating glucose metabolism in pancreatic cancer cells to investigate the value of DKK3 on aerobic glycolysis in pancreatic cancer cells." (PMID 34391478, 2021). "Another study found that the decreased expression of DKK3 is associated with hypermethylation in pancreatic cancer biopsies in comparison to non-tumor tissue." (PMID 32850327, 2020). "Therefore, we investigated the effect of DKK3 on proliferation and apoptosis of pancreatic cancer Bxpc‐3 cell treated by gemcitabine." (PMID 26395974, 2015). "Similarly, immunoblotting showed DKK3 decreased the elevated levels of nuclear β‐catenin induced by hypoxia in pancreatic cancer cells, supporting the result of immunofluorescence." (PMID 26395974, 2015). "In this study, we assessed the expression of DKK3 in pancreatic cancer specimens." (PMID 26395974, 2015). "In this study, we detected DKK3 protein expression in human pancreatic cancer cells." (PMID 26395974, 2015). "Thus, to reveal this question in pancreatic cancer, we examined the changes of β‐catenin localization induced by hypoxia in NC and DKK3 transfectants by indirect immunofluorescence detection of the protein in Bxpc‐3 cells." (PMID 26395974, 2015). "However, further investigations are necessary to probe the detail mechanism of DKK3 in treatment of pancreatic cancer." (PMID 26395974, 2015). "Thus, we examined the function of DKK3 on β‐catenin in hypoxia in pancreatic cancer Bxpc‐3 cell using DKK3‐overexpressing transfectants." (PMID 26395974, 2015). "Dkk3 maintains the pancreatic cancer cells in a dedifferentiated state." (PMID 24926961, 2014). "Heatmap analysis in colorectal, stomach, and pancreas cancer patient datasets showed a consistent overlap between LBH overexpression and WNT signaling genes associated with pathway activation, i.e., WNT2, WNT5A, WNT11, LEF1, TCF4 or TCF7, CCTNB1, CCND1, JUN, DKK3." (PMID 37268816, 2023). "T cells which suggesting that DKK3 may have a therapeutic potential in pancreatic cancer." (PMID 34391478, 2021). "Thus, targeting DKK3 might be an interesting therapeutic approach not only for pancreatic cancer, but also for CP." (PMID 34306986, 2021). "But the specific mechanisms of DKK3 in treating pancreatic cancer remains unknown." (PMID 34391478, 2021).
pancreatic cancer (continued). "However, the function of DKK3 in this pathway in pancreatic cancer is rarely known." (PMID 26395974, 2015). "However, after DKK3 transfection, consistent with the results reported by Xiang, we also found that DKK3 inhibits the nuclear accumulation and the activation of β‐catenin and its downstream genes cyclin D1, c‐Myc in pancreatic cancer Bxpc‐3 cell in normoxia and hypoxia." (PMID 26395974, 2015). "Although pancreatic cancer is similarly resistant to ICB, combined anti-CTLA4 and anti-DKK3 antibodies showed synergistic antitumor responses in a pancreatic cancer model." (PMID 37847565, 2023). "However, the value of DKK3 in pancreatic cancer cells remains unknown." (PMID 34391478, 2021). "Our results demonstrated that DKK3 regulated EMT and improved gemcitabine therapeutic effect in pancreatic cancer." (PMID 26395974, 2015). "Thus, we conclude from our finding that DKK3 is a tumour suppressor and improved gemcitabine therapeutic effect through inducing apoptosis and regulating β‐catenin/EMT signalling in pancreatic cancer Bxpc‐3 cell." (PMID 26395974, 2015). "However, till date, there is rare information as to the expression of DKK3 and its function in EMT and chemotherapy in pancreatic cancer." (PMID 26395974, 2015). "DKK3 alters the metabolic microenvironment of pancreatic cancer cells and further facilitates the function of CD4+ T cells which suggesting that DKK3 may have a therapeutic potential in pancreatic cancer." (PMID 34391478, 2021). "In conclusion, these experiments demonstrated that DKK3 suppresses EMT of pancreatic cancer Bxpc‐3 cell in hypoxic conditions by blocking the translocation of β‐catenin to nucleus, leading to the enhancing of the antitumour effects of gemcitabine in pancreatic cancer Bxpc‐3 cell." (PMID 26395974, 2015). "Thus, we wondered whether DKK3 has an effect on EMT and stem cell properties in pancreatic cancer." (PMID 26395974, 2015). "We also further demonstrated DKK3 down‐regulated stem cell markers OCT4 and induced the decreased number of CD133+ pancreatic cancer Bxpc‐3 cell whether under hypoxia or not." (PMID 26395974, 2015).
colorectal cancer (18 papers, 2013 to 2025). A primary or metastatic malignant neoplasm that affects the colon or rectum. "In GSEA, enriched Dkk3-related signaling pathways in colorectal cancer tissue included those associated with cellular adhesion and migration, melanogenesis, chemokine, Hedgehog, JAK-STAT, TOLL-like receptor, TGF-β, MAPK, and calcium signaling (p<0.05)." (PMID 33425757, 2020). "Altogether, this evidence suggests that downregulated expression or loss of Dkk3 in colorectal cancer cells might disrupt the balance between apoptosis and proliferation." (PMID 33425757, 2020). "Dkk3 mRNA expression was negatively associated with its promoter methylation, growth pattern, differentiation, and favorable prognosis in the patients with colorectal cancer (p<0.05)." (PMID 33425757, 2020). "In addition, colorectal cancer-associated fibroblasts had a higher level of Dkk3 expression compared to that observed in CD133+ or CD133- cancer cells (p<0.05)." (PMID 33425757, 2020). "Functionally, overexpression of DKK3 can decrease cell invasion, proliferation, and colony forming ability in gallbladder cancer cells, colorectal cancer, and lung adenocarcinoma." (PMID 35924156, 2022). "In fact, DKK3 acts as a tumor suppressor by inhibiting tumor cell proliferation, migration and invasion, and promoting apoptosis in gallbladder cancer cells, colorectal cancer, and lung adenocarcinoma." (PMID 35924156, 2022). "Concurrently, the serum level of Dkk-3 was significantly lower in ovarian, gastric, and colorectal cancer patients than in healthy controls." (PMID 33425757, 2020). "Dkk3-related signal pathways in colorectal cancer included those of cellular adhesion and migration, melanogenesis, chemokine, Hedgehog, JAK-STAT, TOLL-like receptor, TGF-β, MAPK, and calcium signaling (p<0.05)." (PMID 33425757, 2020). "Compared with control and mock cells, Dkk3 overexpression suppressed migration and invasion capacities of both colorectal cancer cell types (p<0.05)." (PMID 33425757, 2020). "In conclusion, Dkk3 expression was downregulated in colorectal cancer tissue due to its promoter methylation; this finding can be used in assessing cancer aggressiveness." (PMID 33425757, 2020). "In compare to control cells, Dkk3 protein exposure suppressed migration and invasion capacity of both colorectal cancer cell types (p<0.05)." (PMID 33425757, 2020). "Herein, we observed in vitro and in vivo the effects of Dkk3 expression and recombinant Dkk3 treatment on aggressive phenotypes of colorectal cancer cells, aiming to clarify the molecular mechanisms involved." (PMID 33425757, 2020). "In contrast, serum Dkk3 concentration appeared higher in colorectal cancer patients than in healthy individuals; a similar finding was reported in a study of cervical cancer." (PMID 33425757, 2020). "In both gastric and colorectal cancers, Dkk3 expression was negatively correlated with the depth of invasion, lymph node involvement, and clinicopathological staging; this finding was consistent with that of another study." (PMID 33425757, 2020). "In the present study, expression of Dkk3 mRNA and protein was downregulated in colorectal cancer cells, which is consistent with previous studies." (PMID 33425757, 2020). "Previously, we reported that Dkk-3 is one of the target genes for miR-92a regulation in colorectal cancer cells." (PMID 27827955, 2016). "The miRNA-92a promotesWNT/β-catenin signaling activity by directly targeting KLF4,GSK3β, and Dickkopf-3 (DKK3), which subsequently enhances chemoresistanceof colorectal cancer cells as well as stem cell-like phenotypes to inducecolorectal cancer cell progression." (PMID 40475735, 2025). "A study on colorectal cancer showed that DNMT1 overexpression is associated with promoter methylation of WNT pathway regulators that include WNT inhibitory factor-1 (WIF1), adenomatous polyposis coli (APC), and Dickkopf-3 (DKK3)." (PMID 36765652, 2023). "Dkk3 mRNA expression was examined in colorectal cancer tissues using RT-PCR." (PMID 33425757, 2020).
colorectal cancer (continued). "Here, it was observed that both recombinant Dkk3 protein and Dkk3 overexpression might inhibit cell proliferation and trigger G2 phase arrest in both colorectal cancer cell types." (PMID 33425757, 2020). "The repressing effects of Dkk3 overexpression on aggressive colorectal cancer cell phenotypes might be due to a higher rate of secretion of its soluble form alongside interaction of its cytosolic and other types of protein." (PMID 33425757, 2020). "Recombinant Dkk3 protein and forced Dkk3 overexpression might suppress aggressive phenotypes of colorectal cancer cells." (PMID 33425757, 2020). "Additionally, a higher apoptosis rate was detected in both colorectal cancer cell types exposed to recombinant Dkk3 protein or transfected with Dkk3-expressing plasmid; this finding was consistent with that of our previous study." (PMID 33425757, 2020). "Herein, Kaplan-Meier analysis indicated that mRNA expression or promoter methylation of Dkk3 was not linked to overall survival rate among colorectal cancer patients; this finding was consistent with that of our immunostaining tests." (PMID 33425757, 2020). "Dkk3-related signal pathways included cellular adhesion and migration in colorectal cancer, supporting this hypothesis." (PMID 33425757, 2020). "It has been suggested that expression of cytosolic and secretory Dkk3 protein types might contribute to apoptotic induction of colorectal cancer cells via the mitochondrial pathway." (PMID 33425757, 2020). "Bioinformatics analysis has shown higher levels of Dkk3 mRNA in colorectal cancer; however, this finding might be accounted by between-study differences in methods used (RT-PCR, Western blot, and tissue microarray vs. RNA sequencing)." (PMID 33425757, 2020). "Dkk3-enriched signal pathway in colorectal cancer according KEGG analysis." (PMID 33425757, 2020). "Consequently, Bax hyperexpression and Bcl-2 hyperexpression may explain the inductive effect of Dkk3 in apoptosis of colorectal cancer cells." (PMID 33425757, 2020). "This study investigates four blood-based biomarkers, mSEPT9, IGFBP2, DKK3, and PKM2, for colorectal cancer (CRC) detection." (PMID 39766076, 2024). "Although the mechanism is different, it is consistent with the previous study in colorectal cancer cells; TET1 also inhibits the Wnt pathway indirectly by promoting the expression of Wnt suppressors DKK3 and DKK4 to, therefore, prohibit cell proliferation." (PMID 35805009, 2022). "The results showed that the expression of S100A2, DKK3 and SCHIP1, which play a role in colorectal cancer, HNSC, and gallbladder cancer, was significantly correlated with the expression of LINC00958." (PMID 36437914, 2022). "Moreover, Dkk3 expression had no prognostic significance in colorectal cancer at either mRNA or protein level." (PMID 33425757, 2020). "However, a higher level of Dkk3 expression was detected in the serum of colorectal cancer patients than in that of healthy controls regardless of age (p<0.05)." (PMID 33425757, 2020). "However, Dkk3 protein expression levels did not correlate with gender, age, cell differentiation rate, lymph node or distal metastasis status, peritoneal spread, lymphatic and venous invasion, or tumor size in colorectal cancer patients (p>0.05)." (PMID 33425757, 2020). "Quantitative methylation-specific PCR (qMSP) was used to evaluate methylation of four Wnt-antagonists, SFRP2, WIF-1, DKK3 and SOX17 in 18 normal colorectal mucosa samples, 9 colorectal cancer cell lines, 18 carcinomas, 44 nonpolypoid and 44 polypoid adenomas." (PMID 24350795, 2013). "Previously, we have shown that Dkk3 expression was remarkably downregulated in colorectal non-neoplastic mucosa, adenoma to adenocarcinoma, and negatively correlated with invasion depth, TNM stage, and colorectal cancer cell dedifferentiation rate." (PMID 33425757, 2020).
lung carcinoma (18 papers, 2004 to 2023). "In addition to increasing angiogenesis and the prometastatic potential by DKK3, DKK3 expression is associated with docetaxel chemo sensitivity in lung cancer cells through decreasing expression of the drug efflux pump P-glycoprotein." (PMID 27933272, 2016). "In lung cancer cells, DKK-3 downregulates the expression of survivin at the protein level, and DKK-3 overexpression decreases c-myc and MMP7, which are Wnt signaling effector genes that control the fate of cancer development, progression and metastasis." (PMID 38201279, 2023). "Previously, we have reported on a positive relationship between Dkk3 and Caspase-3 expression in both colorectal and lung cancers." (PMID 33425757, 2020). "The expression of Wnt inhibitory factor-1 (WIF-1) and Dickkopf-related protein 3 (Dkk-3), two endogenous inhibitors of the Wnt pathway, which are frequently downregulated in lung cancer, were upregulated." (PMID 29534536, 2018). "Another Wnt antagonist, DKK3, which is reported to be a tumour suppressor in a variety of malignancies, is able to induce lung cancer cell apoptosis." (PMID 26468775, 2015). "More recently, it has been reported that Dkk-3 expression was reduced by methylation in several cancer cell lines and primary lung cancers." (PMID 15226763, 2004). "In addition, DKK-3 inhibits cisplatin-resistant lung cancer cell growth in a xenograft model of nude mice." (PMID 38201279, 2023). "Our previous study of gastric and lung cancer cells treated with 5-Aza has shown a significantly negative association between Dkk3 promoter methylation and mRNA expression." (PMID 33425757, 2020). "However, since DKK3 promoter hyper-methylation mediated decline in DKK3 expression is shown to result into augmentation of WNT signaling in lung cancer cells, we evaluated the effect of shRNA mediated DKK3 inhibition on testicular WNT signaling." (PMID 23667645, 2013). "A study on lung cancer revealed that the rate of DKK3 methylation increased steadily from normal lung tissue, to low-grade and high-grade atypical adenomatous hyperplasia to invasive adenocarcinoma, suggesting a potential role of DKK3 methylation in lung cancer progression." (PMID 18826564, 2008).